IL10 (interleukin 10)
Diseases named in the same sentence as IL10 in open-access papers (continued):
Sharing a sentence is not in itself a finding about the gene and the disease.
glioma (continued). "Furthermore, by qPCR, IHC, and Western blotting, in different pathological grades of glioma tissues, we found a significant increase in the expression levels of M2-type macrophage-specific markers with increasing tumor grade, including CD206, CD163, ARG1, CD115, and IL-10." (PMID 36033495, 2022). "Additionally, M2-like TAMs secrete IL-10 and TGF-β that play critical roles in tumor immune evasion by inhibiting Th1 and cytotoxic T cell effector molecules, inhibiting antigen presentation by downregulating MHC class II on glioma cells, and attracting immune-suppressive Tregs and MDSCs." (PMID 34503065, 2021). "The research team found that there was an upregulation in IL-10, Osteopontin, MMP14, VEGF, TGF β, and CCL18 in samples containing both human stem cell derived microglial cells with human glioma cells, as opposed to samples containing human glioma cells alone." (PMID 36700223, 2022). "In all glioma patients, we observed a positive correlation of percentage of CD14+ TREM-1+ cells with the IL-6/IL-10 ratio (P = 0.007) and a negative correlation with the plasma levels of IL-10 (P < 0.0001)." (PMID 32684831, 2020). "Both positive (e.g., IFN-γ, IL-10) and negative (e.g., miR-34a, PTEN) signals are involved in the regulation of PD-L1 expression in gliomas." (PMID 30687086, 2018). "IL-10 and CCL-22 were secreted from macrophages at lower levels when the cells were exposed to ACF-pretreated hypoxia-stimulated glioma supernatants than from cells exposed to non-ACF-pretreated hypoxia-stimulated-U87/U251 supernatants." (PMID 27602954, 2016). "Furthermore, STAT3 target molecules such as IL-10 and IL-6 have been shown to activate STAT3, leading Li and Graeber to propose a feed-forward mechanism which may account for the constitutive activation of STAT3 in both glioma cells and glioma-infiltrating TAMs." (PMID 23737783, 2013). "The expression of IL-10 was found to be undetectable at the mRNA level in the homogeneous in vitro cell cultures such as primary glioma cultures and U87MG cell line upon q-PCR analysis (data not shown), thereby indicating the absence of IL-10 production from tumor cells alone." (PMID 35720420, 2022).
influenza (212 papers, 2009 to 2026). An acute viral infection of the respiratory tract, occurring in isolated cases, in epidemics, or in pandemics; it is caused by serologically different strains of viruses (influenzaviruses) designated A, B, and C, has a 3-day incubation period, and usually lasts for 3 to 10 days. "In severe influenza cases, the observed Th2-polarized cytokine profile (marked by elevated IL-4, IL-6, and IL-10 levels) is consistent with established pregnancy-associated immune modulation." (PMID 40558593, 2025). "Third, BLIMP1 was implicated in the expression of IL-10 by an ill-defined ‘T-BET+’ Treg cell subset in a mouse model of influenza infection." (PMID 36973489, 2023). "A previous study has reported that during S. aureus secondary co-infection post influenza infection, IL-27 produced in response to the virus increased susceptibility to S. aureus pneumonia in an IL-10 dependent manner." (PMID 35776778, 2022). "IL-27-/- mice displayed significantly decreased IL-10 production compared to WT mice upon infection with influenza, which led to enhanced bacterial clearance alongside decreased IL-10 production and higher Th-17 associated responses." (PMID 35776778, 2022). "The increased serum levels of IL-6 and IL-10 immediately postoperatively were as high as documented in previous reports of influenza-associated encephalopathy in hypercytokinemia." (PMID 35219343, 2022). "A possible implication is that promotion of Mtb persistence by IL-10 concomitantly increases the risk of death from influenza." (PMID 33746948, 2021). "In the third model, the role of the immunosuppressive cytokine IL-10 was studied during infection by comparing responses in WT or IL-10-deficient mice following influenza infection." (PMID 30641955, 2019). "The prevalence of iBALT in relation to the models of influenza infection discussed here was increased by memory T cell transfer but decreased with the loss of IL-10." (PMID 30641955, 2019). "Our data demonstrated that IL10 is sufficient to exacerbate the morbidity and pulmonary viral load associated with influenza infection (respectively)." (PMID 28086957, 2017). "The role of IL10 in EPFR-induced exacerbation of influenza disease severity was determined by administering recombinant IL10 (rIL10) to wild type mice or by using IL10 deficient (IL10−/−) neonatal mice." (PMID 28086957, 2017). "Further, the percent body weight change in IL10−/−(Air/Flu) mice was significantly higher compared to WT(Air/Flu) mice suggesting that IL10−/− mice are less susceptible to influenza associated morbidity." (PMID 28086957, 2017). "For example, infection with influenza leads to a subsequent increase in susceptibility to bacterial infections, which is mediated in part by excessive IL-10 production in the lungs and increased neutrophil apoptosis." (PMID 26083387, 2015). "In conclusion, our study supports that IL-27 signaling regulates enhanced susceptibility to S. aureus pneumonia following influenza infection, potentially through both the induction of IL-10 and suppression of IL-17." (PMID 25651926, 2015). "Primary infection of IL-10 deficient mice leads to greater resistance against a lethal high dose influenza challenge." (PMID 24465206, 2014). "IL-10 is an anti-inflammatory cytokine that is linked to influenza recovery and the effectiveness of SARS treatment." (PMID 24902603, 2014). "The results suggest that elevated levels of IL-4, IL-6, and IL-10, which are associated with Th2 cell activation, might be related to severe influenza, but the increased TNFα and IFNγ levels also need to be paid attention." (PMID 40558593, 2025). "While all clusters displayed distinct pathway enrichment, Mac3 macrophages strongly downregulate genes associated with proinflammatory processes (Pathogen Induced Cytokine Storm, Hypercytokinemia in Influenza); upregulated genes were associated with the antiinflammatory pathway IL-10." (PMID 38051583, 2024).
influenza (continued). "Both interleukin-10 (Il10), a regulatory cytokine associated with decreased immunopathology during influenza infection, and interleukin-1 receptor like 1 (Il1rl1), the receptor for the alarmin IL-33 that alerts of epithelial trauma, were down-regulated in obese ferrets compared to control." (PMID 38728395, 2024). "Some studies show that IL-10 deficient mice have higher influenza survival rates." (PMID 32974217, 2020). "Since secondary infection leading to pneumonia is a major cause of death in influenza, and perhaps for some COVID‐19 patients as well, excessive IL‐10 production by regulatory T cells may be a key factor in COVID‐19 outcomes." (PMID 33209300, 2020). "In this regard, some studies suggested that SNPs in the IL-10 and IL-1β genes might be associated with the severe outcome in influenza outbreak." (PMID 31196204, 2019). "The elevated levels of proinflammatory cytokines (TNFα, IL-1β and IL-10) during influenza infection have also been primarily associated with increased lung pathology and worse outcomes, but it is uncertain whether some of these cytokines could also be protective during seasonal influenza infection." (PMID 29545521, 2018). "However, the percent body weight change was slightly greater in IL10−/−(DCB/Flu) mice and was statistically different at 9 and 10 dpi compared to WT(DCB/Flu) suggesting that IL10 deficiency can at least partially reduce the EPFR-induced exacerbation of influenza-associated morbidity." (PMID 28086957, 2017). "A high IFN-γ:IL-10 ratio may be associated with protection from influenza." (PMID 23118984, 2012). "Influenza infection increased IL-6, IL-8, IL-10, and CXCL-10 secretion, consistent with previous reports." (PMID 40929365, 2026). "Immunokinetic patterns were pathogen-specific, including transient increase in IL-17A and IL-10 in Legionella and Mycoplasma infections, and CXCL10, IL-2, IL-17A, TGF-β1 and IL-10 in influenza." (PMID 40869413, 2025). "We evaluated serum concentrations of seven cytokines (IL-2, IL-4, IL-6, IL-10, TNFα, IFNγ, and IL-17a) as potential biomarkers for influenza severity in pregnant women." (PMID 40558593, 2025). "Paradoxically, IL-10-producing T follicular helper cells accumulate with age, limiting influenza vaccine efficacy, a process that can be reversed by transient IL-10 blockade." (PMID 39883362, 2025). "Different cytokine profiles were observed compared to influenza and bacterial pneumonia, with IL-2, IL-1β, IL-8, IL-10, CXCL10, and MCP-1 being highest in the AdV group, while free TGF-β1 was lowest in the AdV group." (PMID 39858309, 2025). "This aligns with evidence from influenza, where Tregs prevent immunopathology by secreting IL-10 and IFN-γ." (PMID 41488664, 2025). "Despite the importance of IL-10 in anti-influenza immunity suggested by this study, a review of the literature reveals that the IL-10 production in these 2 mouse strains is stimuli dependent and can lead to opposing outcomes in different diseases." (PMID 38814732, 2024). "In contrast to these proinflammatory cytokines, female immune cells produce significantly fewer anti-inflammatory cytokines such as IL-10 in response to influenza infection or a TLR8 ligand." (PMID 38400083, 2024). "Interleukin-10, a well-known anti-inflammatory cytokine, plays a detrimental role during influenza infection." (PMID 38400083, 2024). "Studies conducted on mice have demonstrated that, at the pulmonary level, butyrate can restore IL-10 levels as well as reduce infections and immunopathology in cases of influenza." (PMID 36979076, 2023). "Pre‐vaccination concentrations of IL‐10 were higher in LRs compared with HRs and inversely correlated with titers of pre‐existing influenza antibodies." (PMID 37457646, 2023). "In contrast, splenocytes isolated from mice vaccinated against influenza vaccination that were exposed to acidic oligosaccharide ex vivo had lower secretion of Th2 cytokines (IL-4, IL-5, and IL-10)." (PMID 38179055, 2023).
influenza (continued). "Meanwhile, IL-10 is a predominant cytokine during influenza infection and plays a role in stimulating the adaptive immune system." (PMID 37754308, 2023). "In our work, high levels of ICOS expression is well aligned with lung tissue resident Treg cell expansion and IL-10 production during flu, suggesting that ICOShigh is a feasible marker for characterizing active lung tissue resident Treg cells in flu models." (PMID 36159872, 2022). "Blockade of PD-1 or ICOS signaling reveals that PD-1 and ICOS signaling pathways counter-regulate TR-Treg cell expansion and IL-10 production, during secondary influenza infection." (PMID 36159872, 2022). "Our data found that expansion and IL-10 production by tissue resident Treg cells during influenza infection was counter-regulated by ICOS and PD-1 signaling." (PMID 36159872, 2022). "Studies have shown that gabexate inhibits the inflammatory expression of IL-6 and IL-10 and attenuates the inflammatory effects of influenza pneumonia." (PMID 35747501, 2022). "The effects of Treg cell depletions are similar to those observed when IL-10 signaling was blocked in acute primary flu and during resolution of primary flu infection." (PMID 36159872, 2022). "Two identified cytokines, IL-6 and IL-10, were shown to be significantly elevated in mice administered CAF09b after influenza infection." (PMID 35163772, 2022). "Our previous studies suggest that the addition of a toll-like receptor (TLR4) agonist to SVV can overcome the suppressive effects of IL-10 and improve the IFNγ response and markedly improve the IFNγ:IL-10 ratio and GrB response to influenza challenge." (PMID 35128529, 2021). "The role of IL-10 in mitigating influenza infection appears to depend on a number of factors, not only the age of the patient, but the strain and dosage of the infecting virus as well." (PMID 33680987, 2021). "Two such cytokines are IL-10 and IL-6, which have been shown to be powerful mediators of inflammation during influenza infection." (PMID 33680987, 2021). "Exogenous expression of IL-10, IL-37, or GM-CSF in the lungs of influenza-infected mice improved survival and recovery from infection." (PMID 33680987, 2021). "Young mice, roughly equivalent to human infants and toddlers, produce less IL-10 in the lungs and at a later time point than adult mice during influenza infection." (PMID 33680987, 2021). "The primary comparison planned was between those older adults randomized to the HD vs. SD formulation of seasonal influenza vaccine using our established methods for measuring cytokine (IFNγ, IL-10) and cytolytic T cell (iGrB) responses to vaccination." (PMID 35128529, 2021). "Total CD4 T cell reactivity at any time point was defined as the total number of cells that produce any of the 4 effector responses (IFNγ, Granzyme B, IL-4 and IL-10) to the different MPs from all 4 influenza strains." (PMID 33922875, 2021). "CD8+ effector T cells produce the anti-inflammatory cytokine IL-10, thereby contributing to resolve lung inflammation during acute influenza infection." (PMID 33828999, 2021). "At 0, 4, 10, and 20 weeks post-vaccination, serum antibody titers, IFNγ, IL-10, and inducible GrB (iGrB) were measured in ex vivo influenza-challenged PBMC." (PMID 35128529, 2021). "Although no studies have yet identified an immune suppressive role for MCs in resolving influenza infection, immune mediators such as IL-10 and IL-6 are known to play an important role in mitigating influenza pathology." (PMID 33680987, 2021). "In contrast, the anti-inflammatory IL-10 response is better preserved and contributes to an overall decline with aging in the IFNγ:IL-10 ratio in response to ex vivo influenza challenge." (PMID 35128529, 2021). "A detrimental effect of IL-10 on the development of Th17-type immune responses and subsequent reduction in survival rate following a lethal challenge with a high dose of influenza has also been reported recently." (PMID 34627297, 2021).
influenza (continued). "Similar to the strong induction of IL-10 in patients with severe influenza, infection of Balb/C mice with a lethal dose (LD100) of H1N1 A/Puerto Rico/8/34 (PR8) induced strong IL-10 expression." (PMID 33680987, 2021). "The effect of prior season influenza vaccination was decreased iGrB levels, and increased IFNγ and IL-10 levels, which correlated with influenza A/H3N2 hemagglutination inhibition antibody titers." (PMID 35128529, 2021). "For instance, a previous study demonstrated that peripheral blood mononuclear cells from males stimulated with influenza and herpes-simplex-1 viruses induced the production of higher levels of IL-10 compared to females." (PMID 34046036, 2021). "In vitro, addition of IL-10 to cultures of splenic CD8+ T cells collected from mice 5 days post-influenza infection halted proliferation of these cells." (PMID 33680987, 2021). "The last study we discussed showed that IL-10 expression inhibits the development of Th17 responses during influenza infection and that this is correlated with impaired protection." (PMID 34064728, 2021). "His death is attributed to the failure of IL-10 to mitigate the influenza-induced inflammatory response, suggesting that IL-10 is vital to tempering severe influenza-mediated inflammation." (PMID 33680987, 2021). "Hemagglutination-inhibition (HAI) titres and IFNγ and IL-10 responses following ex vivo influenza A/H3N2- or B-challenge were measured pre- and post-vaccination and compared between participants who developed LCII and those who did not." (PMID 33430191, 2021). "Hemagglutination-inhibition assays, antibody to Influenza A virus nucleoprotein and peripheral blood mononuclear cells for measurement of interferon-gamma ELISPOT response to influenza antigens, Granzyme B and IFNγ:IL-10 ratio were measured." (PMID 32698532, 2020). "This response appears to be mediated by a 10-fold reduction in IL-10 levels when older adult PBMC are stimulated with GLA-SE plus SVV compared to SVV alone prior to influenza challenge." (PMID 32399058, 2020). "We also observed increased levels of IL-10 in lungs of infected animals; influenza infection has been demonstrated to enhance the production of IL-10, thereby suppressing the overall immune response and promoting susceptibility to secondary infections." (PMID 32922392, 2020). "It is unclear if this applies to specifically Th1-derived IL-10 and if these IL-10 producing Th1 cells are always active during influenza infection." (PMID 32974217, 2020). "Another group of researchers reported the negative regulation of Th17 responses by IL-10 during influenza infection in mice and this effect correlates with defective protection in high dose primary but not secondary challenge infection." (PMID 33391267, 2020). "Surely, more work must be done to understand the role of IL-10 in lung homeostasis during murine and human influenza infections." (PMID 32974217, 2020). "The expression of IL-10 mRNA was significantly higher (p < 0.05 and p < 0.01) in both the Nano-11-based influenza vaccines group compared with the mock group." (PMID 32443416, 2020). "Tregs, typically characterized by their IL-10 secretion, inhibit the function of influenza-specific CD4+ and CD8+ T cells." (PMID 32974217, 2020). "IL-10 can be produced by NK cells and multiple T cell subsets, but the contributions of different IL-10 sources to the host response to influenza is unclear." (PMID 32974217, 2020). "This strategy has previously shown promise as inhibition of certain cytokines, such as IL-10, have shown improved survival from bacterial pneumonia late after influenza infection." (PMID 33202895, 2020). "In the context of influenza infection, however, the role of IL-10 still remains controversial as the genetic background appears to have a dominant effect on disease susceptibility." (PMID 32152316, 2020). "In the spleen, kinetics of IFN-γ or IL-10 secreting T-cells after influenza infection were unaffected by pregnancy." (PMID 32922392, 2020).